BRCA1 (BRCA1 DNA repair associated)
Diseases named in the same sentence as BRCA1 in open-access papers (continued):
Sharing a sentence is not in itself a finding about the gene and the disease.
ovarian carcinoma (continued). "Therefore, mutations in BRCA1/2 are closely related to various cancers, especially breast and ovarian cancer in women and PCa in men." (PMID 35734583, 2022). "Mutations of BRCA1 play an important role in the development of ovarian cancer." (PMID 36230683, 2022). "In addition to breast and ovarian cancer, BRCA1 carriers also have an increased risk of developing other tumors such as prostate cancer and pancreatic cancer." (PMID 35625741, 2022). "The lifetime risk of breast and ovarian cancer in BRCA1 mutation carriers has been estimated to be as high as 87%, and elevated risks of other cancer types, including gastric, pancreatic, prostate and colorectal, have also been identified, with a frequency range of 20–60%." (PMID 36551764, 2022). "Indeed, identifying a BRCA1 PV in a BC patient provides information on her elevated risk of both contralateral BC and ovarian cancer, with all the implications for how to manage those risks." (PMID 35805017, 2022). "However, it should be noted that low-grade ovarian cancers are rare and in that study, 7.3% of all cases (167 out of 2270) were accounted and only 4 cases carried BRCA1 mutation." (PMID 35313928, 2022). "We tested the hypothesis that inhibitor of apoptosis family (IAP) proteins may be altered in BRCA1-mutated ovarian cancers and that could affect the sensitivity to IAP inhibitors." (PMID 35501389, 2022). "Finally, we identified common genetic variations in the CDK5RAP3 locus as potentially associated with breast and ovarian cancer risk in BRCA1 and BRCA2 mutation carriers." (PMID 35053516, 2022). "Moreover, families with ovarian cancer history showed a significantly higher mutation rate in genes other than BRCA1/2 (p value = .001)." (PMID 35608067, 2022). "To test the hypothesis that cellular cAMP suppress DNA damage-induced apoptosis in BRCA1-deficient ovarian cancer cells, we treated BRCA1 knock-down A2780 ovarian cancer cells with ionizing radiation (IR), which induces DNA double-strand breaks." (PMID 35517499, 2022). "Description of the BRCA1/2 mutations in Afro-Colombian families affected by breast/ovarian cancer." (PMID 35641219, 2022). "In addition, clinical trials have evaluated the efficacy of immune checkpoint blockade on BRCA1/2 mutation-associated breast and ovarian cancers, with variable objective response rates." (PMID 36344544, 2022). "Additionally, olaparib possesses approval for first-line maintenance therapy in BRCA variant ovarian cancer as well as approval for maintenance therapy of BRCA1/2 variant pancreatic cancer." (PMID 35685436, 2022). "While most mutations in the genetic code do not significantly alter cellular phenotype, so-called “driver” mutations, such as BRCA1/2, are considered high penetrance mutations that confer women with a substantially higher risk of developing breast and/or ovarian cancer during their lifetime." (PMID 35740550, 2022). "Another important issue concerns the possible role of mutated BRCA1/2 susceptibility genes, which may represent an attractive alternative mechanism in the case of ovarian cancer." (PMID 35163671, 2022). "Patients with mutations in Brca1 are prone to developing breast and ovarian cancer." (PMID 36430332, 2022). "Platinum and PARP inhibitor sensitivity commonly coexist in BRCA1/2-mutated ovarian cancer due to homologous recombination deficiency (HRD); however, nucleotide excision repair (NER) alterations confer enhanced platinum sensitivity but not PARP inhibitor sensitivity." (PMID 36209184, 2022). "Interestingly, lower mRNA expression levels were evident for ovarian cancers with BRCA1/2 mutations." (PMID 36350633, 2022). "Consistent with prior studies of ovarian cancers, our results suggest that BRCA1/2 mutation-associated malignancies accrue most of their genomic scarring and mutations early in tumorigenesis, and increasing genomic instability is not a major factor driving recurrence." (PMID 36344544, 2022).
ovarian carcinoma (continued). "The results show that about one-third of cancers harbor somatic mutations such as BRCA1/2-mutated breast cancer or ovarian cancer and MGMT-methylated glioblastoma, which may give us a hint on the treatment." (PMID 35281059, 2022). "Interestingly, a cell-autonomous STING-driven inflammation and proangiogenic status has also been shown in BRCA1-deficient ovarian cancer cells." (PMID 35393420, 2022). "A BRCA1 or BRCA2 causative variant was found in 18 of 158 (11.4%) unselected ovarian cancer cases." (PMID 35382848, 2022). "The standard of care in BRCA1/2 mutation-associated ovarian cancers is platinum-based chemotherapy (cisplatin, carboplatin) as first line treatment, with poly (ADP-ribose) polymerase inhibitors (PARPi) used increasingly in both the maintenance and metastatic settings." (PMID 36344544, 2022). "Female carriers of a BRCA1 mutation face a higher lifetime risk to develop BC and ovarian cancer." (PMID 35300412, 2022). "To overcome these limitations, we could collect more patients with germline BRCA1 mutations in the future to perform multi-omics single-cell sequencing and determine early-stage events of ovarian cancer in BRCA1 carriers." (PMID 36076202, 2022). "The use of PARP inhibitors has been most successfully exploited in BRCA1/2-deficient breast and ovarian cancers, and recently olaparib has been approved for the treatment of metastatic castration resistant prostate cancer (mCRPC) in patients with DDR gene mutations." (PMID 35545049, 2022). "Whether four mutations (c.1621C > T, c.5251C > T c.4997dupA, c.5251C > T and c.5335delC) in BRCA1 gene are “founder mutations”, predisposing breast and ovarian cancer in the Vietnamese cohort, this needs to be further studied with a larger patient sample size." (PMID 35205313, 2022). "Further studies are needed to assess whether these mechanisms are specific to BRCA1/2 mutation-associated breast and ovarian cancers, or also observed in the context of other tumor types or other DNA repair defects." (PMID 36344544, 2022). "Therefore, we further analyzed the gene mutations within the BRCA1-defective ovarian cancer patients." (PMID 35517499, 2022). "In addition to ADRB1, BRCA1-deficient ovarian cancer cells also express high levels of other factors related to catecholamine-adrenoceptor-cAMP pathway regulation, such as the adenylate cyclase ADCY2 and G protein-coupled receptor ADGRB1." (PMID 35517499, 2022). "Women who had received BRCA1/2 genetic information from lifepool had significantly higher affective ovarian cancer risk perception compared to group 2 (p = 0.0001), whereas there was no observable difference between groups for cognitive ovarian cancer risk perception (p = 0.1)." (PMID 35887609, 2022). "Identifying BRCA1/2 deleterious variants carriers could not only shed light on adjusting chemotherapy schemes, but also contribute to the prevention of ovarian cancer and offspring onset." (PMID 36324133, 2022). "In addition to female breast and ovarian cancers, BRCA1 and BRCA2 PVs are associated with increased risks of male breast, pancreatic, stomach, and prostate (only BRCA2 PVs) cancers, but not with the risks of other previously suggested cancers." (PMID 35077220, 2022). "PARP inhibitors offer a significant clinical benefit for ovarian cancer with BRCA1/2 mutations." (PMID 36267463, 2022). "The lifetime risk of breast and ovarian cancer is 45–80% in BRCA1 and BRCA2 mutation carriers." (PMID 35409996, 2022). "Thus, Brca1 loss is sufficient to predispose ovarian cancer cells to induction of a chemotherapy-induced senescence program that appears associated with improved outcomes in patients." (PMID 35082152, 2022). "This hypothesis was also supported by the positive correlation between AKT3 and BRCA1 IHC expression, a biomarker which has already been associated with stemness-like features and resistance in ovarian cancer." (PMID 35053468, 2022).
ovarian carcinoma (continued). "In unclassified ovarian cancer patients who undertook germline BRCA1 and 2 test, 19% (44/235) were carriers of germline mutations, and somatic mutation test was done on 28 specimens, 42.9% (9/21) and 28.6% (2/7) were found to be BRCA1 and 2 positives, respectively." (PMID 35785170, 2022). "However, mutations in the BRCA1 gene dramatically increase the incidence of breast and ovarian cancers in women." (PMID 35517499, 2022). "Greater than 40% of ovarian cancer patients with BRCA1/2 deficiency fail to respond to PARPi." (PMID 35332131, 2022). "PARPi including Olaparib, Rucaparib, and Niraparib demonstrate significant clinical benefit as maintenance therapy following response to platinum-based chemotherapy in ovarian cancer patients with BRCA1/2 mutation and/or HR-deficiency in both the 1st line and recurrent setting." (PMID 36539830, 2022). "Tumors displaying HRR deficiency, such as ovarian cancer in patients with BRCA1/2 variants, cannot accurately repair DNA damage, and accumulation of such damage may lead to cell death." (PMID 35847868, 2022). "It is known that the expression of the mutated BRCA1 is low in breast and ovarian cancer." (PMID 35869059, 2022). "In our latest study, conducted among consecutive patients with ovarian cancer from the Podkarpacie region (South-Eastern Poland), we observed only 6.3% BRCA1 or BRCA2 founder mutation carriers, and a slightly different spectrum of these mutations than in other regions of Poland." (PMID 35382848, 2022). "Besides breast and ovarian cancers, mutations of BRCA1 and BRCA2 genes also increase the risk of pancreatic and prostate cancers." (PMID 36010291, 2022). "The approximate risk of ovarian cancer is 40% for BRCA1 PV and 20% in BRCA2 PV11,12." (PMID 35469032, 2022). "The prevalence of germline BRCA1 or BRCA2 pathogenic variants (gBRCA1/2-PV) in patients with primary epithelial ovarian cancer (OC) in a rural area of Japan and their association with clinical characteristics, including treatment response and survival outcome, were investigated." (PMID 35741847, 2022). "Multiple studies have proven its efficacy, and PARP inhibitors have shown prolonged progression-free survival and overall survival, providing a median overall survival benefit of 12.9 months in patients with platinum-sensitive, relapsed ovarian cancer and a BRCA1/2 mutation." (PMID 36312861, 2022). "Pathogenic germline variants in these genes confer a high risk for developing breast and/or ovarian cancer that can reach 72% and 44% for BRCA1 mutation carriers and 69% (for breast cancer) and 17% (for ovarian cancer) for those with BRCA2 pathogenic alterations." (PMID 35898894, 2022). "In cohorts of 64 primary and 46 recurrent ovarian carcinoma patients, secondary somatic mutation was detected in 3.1% (2/64) of primary carcinomas and in 28.3% (13/46) of secondary carcinomas (p < 0.05) due to secondary mutations in BRCA1/2." (PMID 35785170, 2022). "Deletion of PARP1 using CRISPR/Cas9 gene editing tools in two ovarian cancer cells (one with BRCA1 mutation and one with BRCA1 promoter methylation) shows >90% reduction of PARP1 expression in BRCA1 mutant and promoter methylated cells as measured by immunofluorescence and western blot analysis." (PMID 35785170, 2022). "Therefore, the aim of this study was to evaluate the effect of BRCA1/2 tumor allele frequency on PARPi response in a unicentric cohort of ovarian cancer patients." (PMID 36143252, 2022). "Germline breast cancer susceptibility gene 1/2 (BRCA1/2) variation is known to increase the lifetime risk of several cancers, such as breast cancer and ovarian cancer, and has been well investigated for its highly ethnic-specific in Ashkenazi Jewish and Polish populations." (PMID 35267488, 2022).
ovarian carcinoma (continued). "Moreover, as BRCA1/BRCA2 mutations are confirmed to be important high-risk factors for the development of ovarian cancer." (PMID 35991556, 2022). "Although the first approved PARPi (olaparib) initially targeted patients with ovarian cancer that carried germline mutations in the BRCA1 or BRCA2 genes, a later study demonstrated responses with olaparib in 41% and 24% of germline BRCA mutation carriers and non-carriers, respectively." (PMID 35203410, 2022). "Besides, the expression of DKK1 in the “cytokine production involved in immune response” pathway was also elevated in BRCA1-deficient ovarian cancer patients." (PMID 35517499, 2022). "Moreover, olaparib maintenance therapy brought substantial PFS benefits with a 70% lower risk of disease progression or death in patients with newly diagnosed advanced ovarian cancer and a BRCA1/2 mutation." (PMID 35466318, 2022). "Similarly, the lifetime risk of developing ovarian cancer is up to 44% for BRCA1 and 17% for BRCA2 variants." (PMID 35685436, 2022). "However, although olaparib shows obvious advantages in the maintenance therapy for patients with PSR ovarian cancer with BRCA1/2 mutation, its high treatment cost limits its feasibility as a clinical treatment option." (PMID 36034834, 2022). "Additionally, a recent study in Algeria on hereditary breast and ovarian cancer families reported only 7 carriers of BRCA1/2 pathogenic mutations out of 113 patients, representing 6.19%, which is lower than ours as well." (PMID 36672847, 2022). "We showed, for the first time, a tremendously improved progression free survival time for 26% of PARPi treated epithelial ovarian cancer patients (with one to four preceding chemotherapy lines) with high corrected variant allele frequencies (cVAF) of either a BRCA1 or a BRCA2 mutation." (PMID 36143252, 2022). "Finally, olaparib is also used for the treatment of adult gynaecological cancer patients with deleterious or suspected deleterious germline BRCA1/2‐mutated (gBRCAm) advanced ovarian cancer who have been treated with three or more prior lines of chemotherapy." (PMID 35567571, 2022). "The impact of BRCA1/2 mutations on steroid hormone activity was assessed by examining endometrial thickness for each menstrual cycle day as an index of hormone regulation in a cohort of 228 women in the UK Familial Ovarian Cancer Screening Study." (PMID 35432218, 2022). "Other common indications include removal of gynecological cancers or risk reduction treatment in women with an inherited increased chance of ovarian cancer as due to gene mutations such as BRCA1, BRCA2 or HNPCC, or those with a strong family history of ovarian cancer." (PMID 35356299, 2022). "This indicates that BRCA1 deficiency predicts poor outcomes for ovarian cancer patients." (PMID 35517499, 2022). "Women with BRCA1/2 mutations are at high risk to develop breast and ovarian cancer." (PMID 35139834, 2022). "Further, BRCA1 c.3770_3771delAG was the most common variant in Chinese ovarian cancer patients." (PMID 36439508, 2022). "Monogenic disease variants and PRS results are reported separately, without comment on any possible interaction between a monogenic result and a relevant PRS (for example, an average-risk BrCa PRS and a pathogenic variant in BRCA1 associated with hereditary breast and ovarian cancer)." (PMID 35437332, 2022). "However, no obvious increase in apoptotic signals was detected in the BRCA1-deficient ovarian cancer patients, indicating that apoptosis was inhibited in the BRCA1-deficient ovarian cancer cells." (PMID 35517499, 2022). "In addition, olaparib treatment in BRCA1-deficient ovarian cancer results in a decrease in granulocyte MDSCs." (PMID 36071479, 2022). "Finally, we identified common genetic variations in the CDK5RAP3 locus as potentially associated with breast and ovarian cancer risk in a large cohort of BRCA1 and BRCA2 mutation carriers." (PMID 35053516, 2022).
ovarian carcinoma (continued). "A high risk of malignant ovarian tumors is observed in women over the age of 49 with a burdened hereditary history (mutations of the BRCA1 and BRCA2 genes, Lynch syndrome, etc.)and after ovarian hyperstimulation, when using hormone replacement therapy, endometriosis, or obesity." (PMID 36359464, 2022). "There are, relatively, many reports that BRCA carriers with common founder mutations have different risks of developing breast and ovarian cancer compared with the overall BRCA1/2 mutation, however, the results of only a few common founder mutations have been validated by multiple studies." (PMID 34356066, 2021). "There are several steps that women with a BRCA1/2 mutation can take to decrease their chances of developing breast and/or ovarian cancer, including prophylactic surgeries (removal of breasts and/or ovaries) and receiving earlier and more frequent cancer screening tests (mammograms and breast MRIs)." (PMID 35052215, 2021). "In 2018, a PARP inhibitor, Olaparib, received full FDA approval for the treatment of BRCA1/2-mutated breast and ovarian cancer, becoming the first therapy to utilize the principle of synthetic lethality, marking a considerable step forward in the pursuit of effective cancer therapeutics." (PMID 34070674, 2021). "Several lines of evidence indicate that specific BRCA1/2 mutations could have prognostic and predictive significance among ovarian cancer patients." (PMID 34898566, 2021). "In the SOLO1 trial (NCT01844986), patients with newly diagnosed advanced ovarian cancers were tested for BRCA1/2 mutation by BRACAnalysis (Myriad) or BRCA1/2 genetic testing assay (BGI) before randomization into olaparib and placebo groups as maintenance therapy." (PMID 34737943, 2021). "A BRCA1 or BRCA2 founder mutations were detected in 54 of the 214 (25.2%) ovarian cancer cases." (PMID 33478551, 2021). "Therefore, many PARP inhibitors have been developed and FDA-approved as anti-tumour molecules for various cancers, such as ovarian cancer, with either somatic or germline BRCA1/2 mutations." (PMID 34363951, 2021). "We observed that the vast majority of the tumors at stage III and IV and of grade 3 were bearing shallow deletions (i.e., expressing one single allele) of both BECN1 and BRCA1, further indicating that the low expression of these tumor suppressor genes associates with ovarian cancer progression." (PMID 33670664, 2021). "Furthermore, TRRAP is a component of a coactivator complex with HAT activity that is required for the transactivation function of the tumor suppressor BRCA1, which is frequently mutated at the onset of breast and ovarian cancer in women." (PMID 33937075, 2021). "BRCA1 gene variants of unclear significance harboured by patients with breast and ovarian cancers." (PMID 34178674, 2021). "The detection of PALB2 and CHEK2 PGVs, in addition to PGVs detected in BRCA1/2, in breast/ovarian cancer is important for accurate risk assessment and the activation of subsequent cancer prevention and early detection strategies in the individual and their family." (PMID 34113003, 2021). "Moreover, in a phase II trial in ovarian cancer patients carrying germ-line mutations of BRCA1 or BRCA2 genes, a synergistic effect of olaparib (PARPis), when combined with durvalumab (ICB), was demonstrated." (PMID 34885169, 2021). "On the other hand, the corresponding correlations for ASA-C and POPA are low and not significant (NS), while the 3-AB induced cytostatic effects were significantly correlated with PARP inhibition only on BRCA1 mutated (presenting “BRCAness”) UWB1.289 human ovarian cancer cells." (PMID 34440232, 2021).